IL1B (interleukin 1 beta)
Diseases named in the same sentence as IL1B in open-access papers (continued):
Sharing a sentence is not in itself a finding about the gene and the disease.
infection (continued). "Thus, it seems plausible that the high levels of IL-1β in PCC reflect this protective role and that post-infection vaccination provides a sufficient refinement of the SARS-CoV-2-directed immune response to clear persisting viral antigens, at least in a subset of PCC patients." (PMID 38316833, 2024). "Thus, it is possible that Salmonella has evolved to depend on IL-1β for host colonization, as infection consistently results in IL-1β secretion, even if not all pathogen-detection mechanisms are triggered." (PMID 38236896, 2024). "Additionally, elevated levels of the cytokines IL-1β and IL-6 were observed in the cerebrospinal fluid of these patients before seizure onset despite the absence of infection." (PMID 39006838, 2024). "Comparison with global inhibition of IL1β, the side effect of infection may not be assumed by specific inhibition of upstream component of this pathway, such as NETs and AIM2 inflammasome." (PMID 39737165, 2024). "In addition, the content of IL-1β at 3 hours and 6 hours post-infection did not significantly increased." (PMID 39353913, 2024). "However, upon infection with DD and up to 6 weeks later, this reduction in IL-1β production was not confirmed after appropriate correction for confounders and intra-class correlations." (PMID 39595313, 2024). "Additionally, mRNA levels of pro-inflammatory cytokines including IL-6, TNF-α, IL-1β, and IL-8 were significantly reduced in BALB/cTFE3-/- mice relative to BALB/cTFE3+/+ mice, suggesting a critical role of TFE3 in viral replication and infection." (PMID 39652582, 2024). "In addition, neutralizing antibody to IL-1β reduced the cell viability of N2aC24L1-3 cells in a dose-dependent manner and increased phosphorylated MLKL in N2aC24L1-3 cells after IAV/WSN infection." (PMID 39194237, 2024). "It has been reported that, after infection with G. parasuis, the expression of p38, ERK, and JNK increased in porcine alveolar macrophages (PAMs) via the NF-κB and MAPK signaling pathways, leading to the upregulation of inflammatory cytokines such as IL-1α, IL-1β, IL-6, IL-8, and TNF-α." (PMID 38927100, 2024). "Thus, the resistance of IL-1β-/- mice to Salmonella is not due to an elevated antimicrobial response as they fail to draw neutrophils to the site of infection." (PMID 38236896, 2024). "Notably, the levels of activated caspase-1 and released IL-1β in response to LPS and ATP, which activate the NLRP3 inflammasome; dsDNA transfection and infection with F. novicida, both as activators of the AIM2 inflammasome, were reduced following transfection with Ncf1, Ncf2, or Ncf4 siRNAs." (PMID 38886341, 2024). "Interestingly, neutralizing IL-1β only reduced infection of LCs and not keratinocytes in the epidermis." (PMID 38793609, 2024). "When comparing QX-314 and vehicle IAV infected mice, we observed a significant decrease in IL-1β and IFNγ, a reduction in the number of interstitial macrophages and CD8 T cells, plus a small improvement in overall lung histopathology all at day 8 post-infection." (PMID 38626267, 2024). "Whereas circulating IL-18 levels were low and showed a decreasing trend without difference between WT and NLRP3−/− mice, levels of IL-1β progressively increased in T. crassiceps-infected WT mice reaching a significant increase in week 8 of infection as compared to NLRP3−/− mice." (PMID 38842647, 2024). "The increase in TNF-α and IL-1β levels during PRRSV infection may contribute to the increase in macroscopic lung lesions and fever in pigs in the challenged group because of the recruitment of additional immune cells to the site of infection." (PMID 38515094, 2024). "When infected with M. tuberculosis H37Rv, an equivalent expression of Il1b and Il6 was detected in mMettl14f/f and mMettl14−/− at 4 h post-infection, indicating that Mettl14 may not regulate macrophages inflammatory response." (PMID 38548762, 2024).
infection (continued). "Our findings also confirmed that T. gondii Wh6 infection upregulated the expression of IL-6, TNF-α and IL-1β in the PFC region, which was restricted by β-glucan, suggesting that the neuroinflammation and cytotoxicity of hyperactivated glial cells could be reduced by β-glucan." (PMID 36782332, 2023). "It revealed that infection of F. necrophorum can induce an inflammatory response in the intertoe skin explants, leading to the activation of the inflammatory pathway of NF-κB, and an up-regulation of the expression of inflammatory cytokines TNF-α, IL-8, and IL-1β." (PMID 37153149, 2023). "Similarly, at 18 h post-infection, OMA had an inhibitory effect on IL-1β, IL -6 and IL-8." (PMID 36992362, 2023). "Since the NLRP3 inflammasome is activated by various PAMPs and DAMPs, such as pathogen infection and its components, bacterial toxin, ATP, silica crystals, etc., we further examined if ODZ could inhibit the release of IL-1β from primary mouse macrophages triggered with various stimuli." (PMID 37047051, 2023). "Notably, IL-1β levels significantly increased in the supernatants of high DBV concentration-treated macrophages (MOI = 1) and reached its peak at 72 h post-infection, in contrast to the macrophages treated with low DBV doses (MOI = 0.01 or 0.1) showing minimal production of IL-1β." (PMID 37486928, 2023). "However, at 72 h post-infection, there was a significant increase of expression of IL-1β in the infected non-obese group as compared to all other time points of the same infected group." (PMID 37047702, 2023). "Furthermore, when measuring biomarkers of inflammation during active infection, analyses with area under the curve (AUC) values above 0.75 indicated that caspase-1, ASC, IL-1β and IL-18 are reliable biomarkers of the inflammatory response during active COVID-19 infection." (PMID 37168848, 2023). "The analysis of the mean expression of cytokines during the infection process showed that the simultaneous injection of two bacteria together with the Leishmania led to a significant decrease in the expression of IFN-γ, IL-1β and IL-10 compared to the control group (P<0.0001)." (PMID 36779192, 2023). "Western blot analysis revealed that the levels of cytosolic proIL-1β and cleaved IL-1β (the biologically active mature form) in the supernatants were markedly reduced following infection with the wild-type strain, but not after infection with the BCG or ShT-N strain." (PMID 37910490, 2023). "Furthermore, no significant release of the inflammasome-regulated cytokine IL-1β was observed in the absence of infection, consistent with inflammasome-independent secretion of pro-IL-18." (PMID 37068092, 2023). "Thus, during viral, but not bacterial infection, IL-1β secretion requires a two-hit system on AMs through initial infection and crosstalk with recruited neutrophils." (PMID 36829255, 2023). "Extracellular MRP8/14, which is a heterodimeric complex released by phagocytes during infection, acts as an endogenous alarmin that amplifies the TLR4 signaling-dependent inflammatory response by inducing proinflammatory cytokines, such as TNF-α, IL-1β, IL-12 and IL-18." (PMID 37701855, 2023). "Although the biological activities of mycolactone during infection are thought to mediate immunosuppressive effects, recent studies have shown that exposure to a low dose of mycolactone can trigger NLRP3 inflammasome activation resulting in IL-1β release from LPS-primed human macrophages." (PMID 37910490, 2023). "The present study investigated whether SaaS mediated the secretion of cytokines in vivo, with the interleukin (IL)-1β, IL-6, IL-18, tumor necrosis factor-α (TNF-α), inducible nitric oxide synthase (iNOS) and cyclooxygenase-2 (COX-2) levels in colon after infection examined with ELISA or RT-qPCR." (PMID 37158502, 2023). "Notably, the infection with S. agalactiae significantly stimulated IL-1β secretion, irrespective of the glucose concentration and the presence of insulin or metformin." (PMID 36982317, 2023).
infection (continued). "Moreover, we found that infection with SADS-CoV induced mRNA expression of inflammatory cytokines such as IL-6, IL-1β, and TNF-α, all of which could be prevented by 17-DMAG." (PMID 36963723, 2023). "Cytokines (IL-1β, IL-6, IL-8, TNF-α, IFN-β, IFN-γ, etc.), mainly derived from mononuclear phagocytes and other antigen-presenting cells, play important roles in defending against pathogen infection and in promoting infiltration of inflammatory cells in tissues." (PMID 38053560, 2023). "The expression level of IL-1β was higher in the group receiving two bacteria plus parasite, as compared to the group receiving two bacteria alone at the beginning and middle of the infection period, but not significantly." (PMID 36779192, 2023). "CA treatment prevented infection-induced production of pro-IL-1β as determined by immunoblotting, and as a result, the impact of the inhibitor on the release of mature IL-1β from the THP-1 cells could not be measured." (PMID 37787552, 2023). "Furthermore, IL-1β and TNF-α can express acute inflammation, infection, and cancer." (PMID 37513454, 2023). "Next, we used enzyme-linked immunosorbent assay (ELISA) to investigate whether SaaS mediated the secretion of cytokines in vivo, with the interleukin-1β (IL-1β), IL-8, and tumor necrosis factor alpha (TNF-α) levels in serum after infection being examined with ELISA." (PMID 36688642, 2023). "The relative expression levels of the necrotic factors Caspase-1, Caspase-3, NLRP3, and IL-1β proteins in placental nourishing cells were higher in patients with multiple genital tract infections compared to those with single infections or no infections in the PROM group (P < .05)." (PMID 38115314, 2023). "During host cell infection with DENV, first, signal 1 is activated: cytoplasmic pattern recognition receptors sense DENV viral RNA and trigger the NF-κB signaling pathway, thereby upregulating the transcription of pro-caspase-1, the NLRP3 inflammasome, pro-IL-1β, and pro-IL-18." (PMID 38249297, 2023). "Since Caspase1 is required for IL-1β activation we hypothesized that cells lacking Caspase1/11 or both Cybb and Caspase1/11 would be unable to secrete IL-1β following infection." (PMID 37314361, 2023). "Since our results showed that L. braziliensis exosome stimulation followed by infection induced high levels of IL-1β secretion by human macrophages, we decided to investigate whether NLRP3 activation is required to drive IL-1β production upon L. braziliensis infection in a murine model." (PMID 37841240, 2023). "Extensive infection leads to the alteration of early cellular gene expression in activated macrophages, followed by sustained release of pro-inflammatory cytokines and chemokines, including TNF-α, MCP-1, IL-1β, IL-6, IL-8, MIP-1α, and MIP-1β, along with reactive oxygen and nitrogen radicals." (PMID 38035334, 2023). "The infection of MDMs with Mtb opsonized with hSAA-1, compared to the infection with nonopsonized bacilli, led to at least a 2-fold increase in the concentrations of CSF2, CSF3, IL-1α, IL-1β, IL-6, IL-12, CCL15, and TNF-α with the most potent 10-fold increase observed for CCL5." (PMID 37781389, 2023). "The canonical proinflammatory cytokines, including IL-1β/IL-6, did not increase after infection, indicating that hBMECs might not be the primary source of inflammatory cytokines in JEV-induced CNS inflammation." (PMID 37752509, 2023). "Thus, IL-1β activates TRPA1 vagus nerve signaling in the afferent arm of a reflex anti-inflammatory response which inhibits cytokine release, induces hypothermia, and reduces the mortality of infection." (PMID 36650454, 2023). "The disruption of the epithelial barrier due to intestinal dysbiosis, infection, and injury results in the entry of bacteria and their metabolites into the bloodstream, which can promote systemic inflammation characterized by elevated plasma TNF-α, IL-6, and IL-1β levels." (PMID 36675302, 2023).
infection (continued). "In addition to NLRP3-derived IL-1β and IL-18, HMPV infection also leads to the over-expression of TNF and IL-6, which can worsen lung inflammation and disease outcomes following infection." (PMID 37508374, 2023). "We only observed a reduction in S205 pyrin dephosphorylation and a significant decrease in IL-1β secretion in response to ∆yopM infection when BMDMs were pretreated with 100 nM OA for 3 h but not for 15 min, which can be explained by the slow entry of the inhibitor." (PMID 37787552, 2023). "The heat map allowed us to visualize the response obtained upon putrescine supplementation with or without L-arginine concomitant to infection, characterized by induction of Nos2 and Arg2, and the response to spermidine supplementation at 4h, with downregulation of Mcp-1 and IL1b." (PMID 37000792, 2023). "Thus, IL-1β activates TRPA1 vagus nerve signaling in the afferent arm of a reflex anti-inflammatory response to inhibit cytokine release, induce hypothermia, and reduce the mortality of infection." (PMID 36650454, 2023). "RT-qPCR did not reveal significant differences in the amount of TMEV RNA as well as Ifnb1, Isg15, Eif2ak1 (PKR), Tnfa, Il1a, Il1b, Il6, Il10, Il12 (p40) and Ifng transcript numbers in the brain of Asc−/− and Casp1−/− mice and their respective wild type littermates at 4 days after TMEV infection." (PMID 37414913, 2023). "Previous studies in a fish model of infection with A. hydrophila demonstrated the expression of RELA gene and the NF-κB pathway that could result in the production of several cytokines such as TNF-α, IL-1β, IL-12, IL-8, IL-6, and IFN." (PMID 35874671, 2022). "The results showed that L. garvieae colonies could be isolated at 6, 12, 24, and 48 hours after infection with planktonic and biofilm bacteria.For the TLR2, IL-1β gene, we found that it was upregulated at 6, 12, and 24 hours and downregulated at 50 hours after infection in the planktonic group." (PMID 35677656, 2022). "Despite this difference in cytokine gene expression, levels of TNFα & IL-1β in BALF were generally similar for the Hi2019WT and Hi2019ΔlldD strain except for IL-1β levels at 6 h post-infection where lower levels were observed for infections with the mutant strain." (PMID 35085362, 2022). "We investigated whether infection with the P. aeruginosa strain, PAO1, induced expression of components of the NLRP3 inflammasome and found that a 6-h infection significantly increased expression of NLRP3, the adapter protein ASC, caspase-1, IL-1β, and IL-18 in BEAS-2B bronchial epithelial cells." (PMID 35215060, 2022). "Also similar to our results with macrophage cell lines, Δ51-infected WT primary BMDM secreted increased interleukin 6 (IL-6) and IL-1β and accumulated ROS, unlike in WT or Δ51C infection." (PMID 35467412, 2022). "However, we did not detect a significant increase in the serum IL-1β levels throughout CHIKV infection (1 to 16 days) compared with prior infection in all the mice." (PMID 36377866, 2022). "Furthermore, IL-1β not only acts as a signaling molecule needed for the production of inflammatory cytokines; our experimental evidence also indicated that the IL-1β is a negative regulator of IFN-β production in particular PA infection." (PMID 36190409, 2022). "Since 20% of participants in both cohorts report resolution of PASC between 4 and 12 weeks after infection, we asked whether there are trends toward normalization of IL-1β, IL-6, and TNF levels with elapsed time after infection in individuals reporting ongoing symptoms." (PMID 35732153, 2022). "Interestingly, phiMR003 also suppressed the IL-1β and IL-6 levels induced by KYMR58 infection." (PMID 36123529, 2022). "In particular, the transcription level of some cytokines in the splenic lymphocytes, including IL-1β, IL-6, IL-8L1, and CCL4, which are related to B cell activation and antigenic signal transduction to T cells, were significantly upregulated by MDV/CVI988 infection compared with MDV/RB1B infection." (PMID 36680047, 2022).
infection (continued). "In addition, NLRP3 and CASP1 expression was increased at low MOI in both strains, while IL-1β was independent of virulence but dependent on infection MOI, suggesting the activation of pyroptosis." (PMID 35631013, 2022). "Despite the increased number of neutrophils in the lung, we failed to observe a rise in the expression of the pro-inflammatory cytokines, TNFα, IL1β or IL-6, in the lung of aged mice after infection, when compared to the lungs of young-infected mice (data not shown)." (PMID 35392033, 2022). "Thus, it has been recently described that GSDME, a protein related with pyroptosis and IL-1β release, is activated in neutrophils in a RIPK1-dependent manner and that the FADD-RIPK1-caspase 8 complex is recruited after infection to cleavage GSDMD and initiates the inflammatory cell death." (PMID 35716229, 2022). "Furthermore, the use of neutrophils from elastase-deficient mice confirmed that serine proteases were not required for IL-1β processing in this infection model." (PMID 35406754, 2022). "Although we cannot exclude that lower bacterial loads in MRP8Cre+Casp1flox mice could influence the levels of IL-1β measured in BALFs, those results suggest that neutrophil Caspase-1 is also a contributor of IL-1β production upon PAO1, PAO1ΔExoS and PP34ExoUS142A infections." (PMID 35849616, 2022). "In glial cells, Tha and Th2P-4M infection did not induce significant expression of the selected proteins, although modest modulations of constitutively expressed proteins (IL-1β, IL-6, LIF) that were detected in astrocytic cells and/or in microglia-like HMC3 were recorded." (PMID 36680128, 2022). "Similarly, although there was a considerable increase in these groups compared to the control group, the cytokine content of IL-1β did not change between the infection and coinfection groups." (PMID 36556283, 2022). "The sensitivity and range of the IL-1β measurement ELISA kit we used were 0.063 pg/mL and 0.1–8 pg/mL, respectively, so if there had been no particular infection, the serum IL-1β concentration would have been lower than this, suggesting difficulty in quantification using current ELISA kits." (PMID 35887537, 2022). "While infection of Il-1r−/− mice provides a model in which no IL-1β signaling is allowed since the onset of infection, it fails to exclude differences in heart physiology/immunological response that might reflect the role of IL-1β in mouse development." (PMID 36341442, 2022). "Interestingly, EV-A71 infection failed to induce IL-1β release in cells that lacked RIG-I and NLRP3 expression." (PMID 36503883, 2022). "During the infection, we also observed increased production of IL-1β in turbot, however, no mature IL-1β was detected, suggesting that CASP3/7 and CASP6 may not be involved in processing pro-IL-1β." (PMID 35610210, 2022). "Furthermore, it moderately increased the expressions of proinflammatory cytokines including IL-1β, IL-6, and TNF-α in the early stage of infection and decreased their release rapidly in the later stage, while regulated the same phase change of anti-inflammatory cytokine IL-10." (PMID 35071595, 2022). "However, the primary infection additionally induced G-specific humoral responses in sera, which were of course absent after Ad-F-Ad-IL-1β immunization." (PMID 36003372, 2022). "Similarly, E. coli 1587 infection dramatically stimulated the upregulation of IL-1β, IL-6, IL-10, and TNF-α mRNA transcription levels in mice colons 3 days post infection, but this phenomenon mostly diminished by 7 days post infection except for IL-6." (PMID 35399688, 2022). "The present study, revealed the significant up-regulation of pro-inflammatory cytokines, such as, IL-1β, IL-6, IL-10, IFN-γ and non-significant elevation of TNF in infected controls on the 9th day post-infection, showing an association with disease severity that supports previous findings." (PMID 36510199, 2022).